PPARA (peroxisome proliferator activated receptor alpha)
Diseases named in the same sentence as PPARA in open-access papers (continued):
Sharing a sentence is not in itself a finding about the gene and the disease.
dyslipidemia (continued). "An anti-inflammatory activity of 2-AG could also sustain reduced systemic inflammation following PPARα activation by FBR, as observed in subjects with metabolic syndrome." (PMID 36614161, 2022). "Saroglitazar, a dual-PPARα/γ agonist, in a randomized, double-blind, placebo-controlled study (EVIDENCES IV, NCT03061721), significantly improved liver function, serum ALT, insulin resistance and atherogenic dyslipidemia." (PMID 35625520, 2022). "The non-CHD indications of clinically used drugs included dyslipidemias (PPARA), type 2 diabetes (PPARG and NDUFA13), autoimmune diseases (TNF), neoplasms (RAF1 and PSMA5), circulatory disorders (ABCA1, PLG, ITGB3, and F2), and alcohol-dependency (ALDH2)." (PMID 34675202, 2021). "Another antidiabetic drug elafibranor (GFT505), a dual PPARα/δ agonist, can improve NASH and multiple cardiometabolic risk factors associated with metabolic syndrome and T2DM without worsening fibrosis at a dose of 120 mg/d for one year." (PMID 34299189, 2021). "Pemafibrate, a selective PPARα modulator, has the beneficial effects on serum triglycerides (TGs) and very low density lipoprotein (VLDL), especially in patients with diabetes mellitus or metabolic syndrome." (PMID 33610176, 2021). "Hence decreased expression of PPARα in PWH is relevant, because PWH are reported to have an increased prevalence of impaired MFO, metabolic syndrome, inflammation, insulin resistance, endothelial dysfunction, and cardiovascular disease." (PMID 33007928, 2020). "Furthermore, hypermethylation of the promoter regions of PPARα and CTP1A genes was shown in a model of high fructose-induced metabolic syndrome in rats." (PMID 32577122, 2020). "Therefore, we will not discuss the clinical efficacy of both approved (fenofibrate, bezafibrate, gemfibrozil) and investigational PPARα agonists (LY518674, ZYH7, GW590735, K-111) in dyslipidemia." (PMID 31614690, 2019). "Our results suggest that the mechanism of DLS anti-diabetic and relieving dyslipidemia may up-regulate the expressions of p-MAPK, GLUT4, and PPARα." (PMID 31340585, 2019). "Elafibranor (also known as GFT505), which is a dual-PPARα/δ agonist, has shown a potent ameliorative effect on insulin resistance, hyperglycemia and dyslipidemia in obese patients with impaired glucose tolerance without significant safety concern." (PMID 31614690, 2019). "Finally, the miR-21/PPARα axis was found amplified in liver and muscle biopsies, and in serum, of NAFLD patients, co-substantiating its role in the development of the metabolic syndrome." (PMID 28406477, 2017). "Similar to Pparα- andPgc1α-deficient mice, fat accumulation is more pronounced inRap1-deficient females than in males, and they developpathologies that are reminiscent of metabolic syndrome in humans, further supportingthat RAP1 and PPARα are in the same pathway for regulation ofmetabolism." (PMID 23791526, 2013). "The PPARα-agonists (e.g. fibrates) play a central role in reducing plasma concentrations of TG-rich lipoproteins, increasing HDL-C levels and reducing vascular inflammation in people with atherogenic dyslipidemia." (PMID 23721199, 2013). "Adiponectin stimulation of fatty acid degradation is mediated by PPARα and CAR inhibition of this pathway might further contribute to promotion of a metabolic syndrome." (PMID 19691840, 2009). "Taken together, the nexus of PPARα (albeit weakly activated in humans; Takacs and Abbott (2007)), CAR, and PXR activations under PFOS exposure implicate dysregulations of energy homeostasis (particularly dyslipidemia) and consequent widespread adverse physiological effects." (PMID 40809130, 2024). "Hence, the present study was undertaken to assess the mechanistic hepatoprotective roles of resveratrol against changes contributed to HFFD-induced metabolic syndrome in rats via evaluation of oxidative/antioxidant molecules, NF-kβ signaling, lipid-related genes (SREBP1-c/PPARα), and IRS-2." (PMID 35990819, 2022).
dyslipidemia (continued). "The anti-dyslipidemia effects may be involved in the downregulation of adipogenic and lipogenic genes (C/EBP-α/-β, SREBP1, PPARγ, and FAS) and the upregulation of genes exerting transcriptional roles in lipolysis and β-oxidation (PPARα and UCP2)." (PMID 35326230, 2022). "The present study was undertaken to investigate the effects of A. sinensis flowers on PPARα, PPARγ and LXR activation, adipogenesis and glucose uptake in hepatocytes, adipocytes and differentiated myoblasts with the aim to establish its potential in ameliorating the condition of metabolic syndrome." (PMID 35163893, 2022). "Previously, we studied PPARα expression levels in diabetics with and without dyslipidemia (DD)." (PMID 36142760, 2022). "The oral administration also ameliorates NAFLD and dyslipidemia with lower liver damage and adiposity indices, together with a reduction in the blood levels of triglycerides and total/LDL cholesterols and downregulation of hepatic genes involving lipid synthesis (e.g., SREBP1c, FAS, and PPARα)." (PMID 36005486, 2022). "Therefore, SREBP1c, FAS, PPARα, LXR, CYP7A1, and ABCA1 mRNA expression levels were evaluated in our study to investigate whether green tea leaf powder could influence the dyslipidemia in HFD-fed mice." (PMID 33281537, 2020). "In humans, fibrate activation of PPARα has been shown to increase the circulating levels of atheroprotective HDLc, to lower plasma levels of TG and FFA, and to improve overall atherogenic plasma lipid profiles while exerting beneficial effects on inflammation, IR, and metabolic syndrome." (PMID 30428868, 2018). "PPARα is activated by polyunsaturated fatty acids, like docosahexaenoic acid (DHA) and icosapentaenoic acid (EPA), and by fibrate drugs like gemfibrozil and fenofibrate, which are currently used as a treatment for dyslipidemia, metabolic syndrome, and cardiovascular damage." (PMID 25246934, 2014). "In an attempt to restore the metabolic alterations that could be leading to death in T. gondii infection in the absence of CCR5-/-, mice were treated with Gemfibrozil, a PPARα agonist used in the treatment of dyslipidemia." (PMID 25119429, 2014). "Thus consistent with in-vitro PPARα transactivation data, the in-vivo results in hamster further corroborated the powerful potency of ZBH relative to the clinical widely used drug bezafibrate in ameliorating dyslipidemia." (PMID 24759758, 2014). "It is possible that PPARα may inhibit the activity of a degenerin channel, possibly ASIC2 or a hybrid ENaC–ASIC channel, that has yet to be identified in hepatic cells, and disruption of this regulatory system in the liver may be a driver for metabolic syndrome development." (PMID 39224121, 2024). "Then, in our study, it was found that there was no significant change in PTEN and PPARα in miR-21a-5p KD mice, we thought the result might reflect a compensatory mechanism of the organism under the stimulation of pathological stress of dyslipidemia after the miR-21a-5p knockdown." (PMID 34099844, 2021). "Pemafibrate is a highly selective PPARα modulator, and treatment with pemafibrate reduces serum triglycerides and increases high density lipoproteins (HDL) cholesterol in patients with dyslipidemia and metabolic diseases without deleterious side effects." (PMID 40263984, 2025).
Insulin resistance (438 papers, 2005 to 2026). Increased resistance towards insulin, that is, diminished effectiveness of insulin in reducing blood glucose levels. "Disruption of circadian rhythm, peroxisome proliferator-activated receptor α (PPARα) signaling (a contributor to insulin resistance and T2DM), and AhR activation are implicated in T2DM development in individuals exposed to environmental pollutants." (PMID 41440753, 2025). "PPARα-null mice were protected against HFD-induced insulin resistance, and PPARα deficiency reduced insulin resistance in apoE-null mice." (PMID 35655996, 2022). "Recent experimental studies strongly suggest that decreased hepatic PPARα expression positively correlates with insulin resistance and NASH severity, while NASH resolution is associated with an upregulation of PPARα as well as its target genes." (PMID 35203484, 2022). "Other data have demonstrated that the loss of Arid1a enhances NAFLD by downregulating PPARα, thereby blocking fatty acid oxidation and leading to lipogenesis and insulin resistance." (PMID 36432495, 2022). "An important feature of PPARα transgenic mice is the lipid accumulation in the heart, in which, diacylglycerol is closely associated with cardiac insulin resistance, while elevation of ceramide is related to cardiac dysfunction." (PMID 33397369, 2021). "PPARα was previously shown to mediate fatty acid oxidation in liver, while PPARγ is linked to insulin resistance and lipid storage in adipocytes." (PMID 32728158, 2020). "At a placental level, adiponectin causes insulin resistance by activating PPARα and inhibiting insulin receptor substrate 1 phosphorylation, which reduces insulin responsiveness." (PMID 33029393, 2020). "A high-fructose diet has been associated with insulin resistance and dyslipidaemia, as well as causing inflammation and reduction of peroxisome proliferator-activated receptor alpha (PGC1A) in animal models." (PMID 31647549, 2019). "Studies conducted by many researchers have shown that lower PPARα expression favors hepatic glucose production and is also correlated with insulin resistance, causing deterioration of NAFLD." (PMID 29158770, 2017). "PPARα downregulation, which further upregulates the SREBP-1c/PPARα ratio, predisposes obese patients to insulin resistance and hepatic steatogenesis." (PMID 29018509, 2017). "Simultaneous activation of PPARα, PPARδ and PPARγ by a single compound is being pursued to treat the multiple defects associated with insulin resistance, type 2 diabetes and the metabolic syndrome." (PMID 25143786, 2014). "The activation of PPARα in diabetes is due to both the increased intake of dietary fatty acids, in addition to increased adipose lipolysis associated with adipose insulin resistance." (PMID 24063408, 2013). "Environmental factors, such as dietand exercise and genetic factors influence PPARα, γ activity as well as the risk for insulin resistance and GDM." (PMID 18288290, 2008). "Thus, PPARα activation in the liver provides a mechanism underlying AhR-mediated insulin resistance, while AhR deficiency protects mice from insulin resistance, potentially via PPARα downregulation." (PMID 41440753, 2025). "PPARα agonists enhance adiponectin production, which may also be beneficially associated with systemic insulin resistance." (PMID 37895151, 2023). "Moreover, some studies reported DNA methylation profiles in several genes related to RXRA, SREBF1, PPARA, etc., closely associated with age-related susceptibility to hepatic insulin resistance and increased liver lipid metabolism." (PMID 37201099, 2023). "Furthermore, a hepatic androgen receptor deficiency decreases fatty acid oxidation and increases hepatic de novo lipogenesis by decreasing PPARα expression, which causes hepatic steatosis and insulin resistance." (PMID 38075062, 2023). "Further, PPARα agonists enhance adiponectin production, which may be also beneficially associated with systemic insulin resistance and inflammation." (PMID 35408799, 2022).
Insulin resistance (continued). "PPARα regulates the expression of genes encoding proteins that are involved in lipid metabolism, fatty acid oxidation and glucose homeostasis, thereby improving markers for atherosclerosis and insulin resistance." (PMID 23226761, 2012). "PPARα is a key gene that modulates lipid deposition, and several direct pieces of evidence indicate that selective PPARα activation significantly reduces body weight gain and insulin resistance in rodents after HFD by regulating fat-metabolism associated gene expression." (PMID 28445156, 2017). "PPARα/δ dual agonists may improve hyperlipidemia,insulin resistance, and risk of atherosclerosis." (PMID 18566691, 2008). "Increased activity of PPARα results in insulin resistance and defects in insulin signalling and STAT3 activity, reducing cardiac function." (PMID 41007642, 2025). "Although changes in lipid profile and insulin resistance, assessed using the TyG index, were modest, saroglitazar’s dual PPARα/γ activation provides a mechanistic advantage by targeting multiple metabolic pathways." (PMID 41583325, 2025). "Compared with PPARα agonist alone, apoA-I has the advantages of not only relieving insulin resistance and lipid accumulation but also improving atherosclerosis." (PMID 39940822, 2025). "PPARα/γ agonists like saroglitazar improve insulin resistance, suppress SREBP1c-mediated lipogenesis, and attenuate oxidative stress via nuclear factor erythroid 2 like 2 (NRF2) activation, demonstrating efficacy in preclinical steatosis and fibrosis models." (PMID 40564141, 2025). "Pharmacological activation of PPARα has beneficial effects on glucose homeostasis, insulin resistance, inflammation, and hyperlipidemia." (PMID 41438090, 2025). "Transplantation also increased GLUT4 expression to improve insulin-resistance in adipocytes and skeletal muscles through PPARα activation, as well as improved pancreatic function through PPARα and PPARγ activation." (PMID 38505622, 2024). "Jansen’s team observed that 1,2-Dilinoleoyl-sn-glycero-3-phosphocholine enhances adipocyte catabolism and apoptosis through a TNF-α-dependent pathway, thereby alleviating insulin resistance via PPARα-mediated inhibition of myocyte inflammation." (PMID 39050247, 2024). "Elafibranor, a PPARα/δ agonist, improves insulin resistance and inflammation, and has shown promise in early clinical trials." (PMID 38539547, 2024). "IRF9 regulates interferon-driven gene expression, and alleviates hepatic insulin resistance, steatosis and inflammation through interaction with PPARα." (PMID 39350187, 2024). "For example, PPARα agonists treat hyperlipidemia or modulation of inflammatory response, while PPARγ agonists have potent hypoglycemic potential in patients with insulin resistance and cancer." (PMID 39062500, 2024). "Therefore, a reduction of PPARα may cause insulin resistance and promote EMC." (PMID 37305395, 2023). "PPARα agonists can induce the browning of white adipose tissue, leading to an improvement in systemic insulin resistance." (PMID 37895151, 2023). "chiglitazar sodium, a PPAR agonist, activates PPARα, γ, δ, reduces insulin resistance, effectively controls blood sugar and improves the disorder of blood lipid and energy metabolism often associated with T2DM patients, with good safety." (PMID 37987033, 2023). "Visceral adiposity and insulin resistance are negatively correlated with liver PPARα gene expression." (PMID 37895151, 2023). "Zhang Q., Kong X., Yuan H., Guan H., Li Y., Niu Y. Mangiferin improvedPalmitate-induced-insulin resistance by promoting free fattyacid metabolism in HepG2 and C2C12 cells via PPARα: mangiferinimproved insulin resistance." (PMID 37469453, 2023). "Deletion of hepatic PPARα resulted in decreased beta oxidation, insulin resistance and increased liver lipid accumulation." (PMID 37173315, 2023).
Insulin resistance (continued). "MUFA protects against SFA-induced inflammation and insulin resistance by promoting triglyceride accumulation and mitochondrial beta-oxidation through peroxisome proliferator-activated receptor-alpha (PPAR-α) and protein kinase A-dependent mechanisms." (PMID 37340168, 2023). "In non-alcoholic fatty liver disease (NAFLD), KLF16 improves steatohepatitis and insulin resistance by targeting PPARα." (PMID 37391422, 2023). "When 18-month-old mice were fed an HF diet for 4 weeks, WT mice showed more severe insulin resistance than PPARα−/− mice." (PMID 36140300, 2022). "Studies have shown that saroglitazar, a dual agonist of PPARα/γ, improves insulin resistance and steatohepatitis in NASH mice." (PMID 35178098, 2022). "Clinical studies have shown that the increased expression of PPARα in the human liver can alleviate visceral obesity and insulin resistance while improving the effect of histology." (PMID 35035496, 2022). "In this study they demonstrated that hepatic vagotomy attenuated hyperinsulinemia, hyperglycemia and insulin resistance through decreased expression of hepatic PPARα." (PMID 36389223, 2022). "A previous study reported that betaine upregulated PPARα and ameliorated lipid accumulation and insulin resistance in fructose-induced nonalcoholic fatty liver disease." (PMID 35327303, 2022). "Activation of the JNK pathway, which drives HFD-induced insulin resistance, increases the expression of Ncor1 and Nrip1 co-repressors to negatively regulate PPARα target expression." (PMID 36589809, 2022). "Activation of PPARγ systemically decreases the insulin resistance while PPARα reduces both plasma cholesterol levels and insulin resistance in the body." (PMID 36302045, 2022). "Activators of both PPARα and PPARγ have been shown to improve insulin sensitivity and normalize impaired glucose tolerance in both humans and rodent models of insulin resistance." (PMID 34899310, 2021). "Elafibranor, or GFT505, is a dual PPARα/δ agonist that showed promise in early clinical trials, leading to improved serum lipid profiles and insulin resistance in dyslipidemic and prediabetic/diabetic patients, respectively." (PMID 34298687, 2021). "N-3 polyunsaturated fatty acids (PUFAs) were shown to reduce hepatic lipid synthesis and insulin resistance via regulating the expression of PPARα and SREBP-1, which were expressed with diurnally rhythms according to circadian clock." (PMID 36994336, 2021). "Typical exogenous ligands for PPARα and PPARγ are bezafibrate and pioglitazone, respectively, which are used as PPAR agonists to treat hyperlipidemia and insulin resistance, respectively." (PMID 35052547, 2021). "Investigations have shown that fenofibrate inhibits adipocyte hypertrophy and insulin resistance by activating adipose PPARα in HFD-induced obese male mice." (PMID 35011564, 2021). "In the validation of pathways, key targets (INSR, PTPN1, PPARA, and PPARG) from two of the most significant pathways in pathway enrichment analysis, Insulin resistance, and PPAR signaling pathway, were selected." (PMID 34579756, 2021). "AQ also improves insulin resistance and lipid metabolism in diabetic model mice by activating PPARα/γ and thus can be useful in preventing and treating type 2 diabetes." (PMID 34808194, 2021). "In in vivo models of insulin resistance and diabetes, PPARα activation reverses the pregnancy-related augmentation of glucose-stimulated insulin hypersecretion by increasing insulin sensitivity." (PMID 32708786, 2020). "In fact, PEA and OEA are known to play an important role in the modulation of many biological functions, including energy balance, inflammation, and insulin resistance, likely via the activation of PPARα." (PMID 32235294, 2020). "The activation of PPARα can improve hepatic insulin resistance by reducing the accumulation of deleterious lipids." (PMID 32878157, 2020).